NPY (neuropeptide Y)
Diseases named in the same sentence as NPY in open-access papers (continued):
Sharing a sentence is not in itself a finding about the gene and the disease.
colorectal cancer (11 papers, 2013 to 2024). A primary or metastatic malignant neoplasm that affects the colon or rectum. "In addition, our data adds further information that NPY methylated ctDNA is detectable in practically every colorectal cancer patient, correlates with RAS/RAF mutated ctDNA, and has the same prognostic information." (PMID 31731482, 2019). "Y2R antagonists inhibited tumor growth and NPY-induced angiogenesis in colorectal cancer, and the Y2R antagonist BIIE0246 decreased melanoma tumor weight, angiogenesis, and serum VEGF level." (PMID 37373115, 2023). "Methylated NPY in circulating tumour DNA is currently a major focus for cancer biomarker detection in colorectal cancers." (PMID 36329447, 2022). "In conclusion, NPY methylated ctDNA was a universal liquid biopsy marker in colorectal cancer patients treated with regorafenib." (PMID 31731482, 2019). "We conducted our study to determine whether serum orexigenic neuropeptide Y (NPY) concentration is associated with nutritional status and prognosis among patients undergoing surgery for colorectal cancer (CRC)." (PMID 39599612, 2024). "In this context, a study has reported that hypermethylation of the NPY gene in circulating tumor DNA could be a biomarker for colorectal cancer screening and diagnosis." (PMID 37373115, 2023). "In the present study, we propose a panel of tumor-specific methylation genes (NPY, PENK, and WIF1) which in combination show a potential as epigenetic markers for the colorectal cancer diagnosis." (PMID 24289328, 2013). "Thus, the hypermethylated promoters of NPY and WIF1 are specific early markers of colorectal cancers but their roles in CRCS carcinogenesis are not clearly established." (PMID 34627187, 2021).
mood disorder (11 papers, 2013 to 2024). A cognitive disorder a disturbance in which the person's mood is hypothesized to be the main underlying feature. "The INF contains two distinct populations of neurons, the pro-opiomelanocortin (POMC)-expressing neurons and the neuropeptide Y (NPY)-expressing neurons, that are both involved in mood disorders (MD) and suicide." (PMID 38263257, 2024). "The relationships between NPY and mood disorder and between NPY and bone mass maintenance are intriguing and need further investigations." (PMID 35273572, 2022). "The antidepressant efficacy of the Y5R antagonist, Lu AA33810 is in line with observations of many authors who evidenced an important role of NPY in mood disorders (see Introduction)." (PMID 27975125, 2017). "NPY is one of the most abundant peptides in the central nervous system and mediates mood disorder, stress response and antidepressant effect mainly through the Y1 and Y2 receptors, which are densely expressed in the cortex, hippocampus and amygdala." (PMID 28082897, 2016). "Therefore, we performed the immunohistochemical analysis for NPY expression in the hippocampus, as this neuropeptide was found to be involved in pathogenesis of various mood disorders, including alterations in depressive state levels." (PMID 28582442, 2017). "Even though previous studies have shown that NPY participates in bone metabolism, especially in the bone formation process and BMSC fate decision, the effect of NPY on osteoclastogenesis and mood disorder is not fully understood." (PMID 35273572, 2022). "However, Y2R and Y5R, which are distributed mainly presynaptically, may negatively regulate NPY release, and antagonism of Y2R and/orY5R would thus be expected to increase NPY function in the CNS and may prove to be useful in treating mood disorders." (PMID 27975125, 2017).
Stroke (11 papers, 2012 to 2025). Sudden impairment of blood flow to a part of the brain due to occlusion or rupture of an artery to the brain. "Several population‐based studies have demonstrated that elevated NPY level is associated with cerebral vasospasm and consecutive stroke due to subarachnoid haemorrhage." (PMID 39575855, 2025). "NPY polymorphism was suggested to be a genetic risk factor for the incidence of stroke, suggesting the possible involvement of NPY systems in stroke pathology mechanisms." (PMID 39575855, 2025). "Around the same time, our research group also reported that the C-399T variation of the neuropeptide Y (NPY) gene was associated with the Dampness-Phlegm pattern in Korean stroke patients." (PMID 22927882, 2012). "In the current study, we examined the association of the dampness-phlegm pattern of stroke with five SNPs of the NPY gene among Korean CI patients and found that the C-399T SNP was negatively associated with dampness-phlegm pattern (OR = 0.663)." (PMID 22110543, 2012). "Our findings were consistent with the evidence of a high frequency of NPY polymorphism in stroke patients, especially the small vessel disease subtype, the profound effect of NPY on the small arterioles of the brain, and direct action on vascular endothelial cells." (PMID 39575855, 2025). "Overall these results confirm the remarkable resistance of SOM+ and NPY+ cells up-to 2 weeks after stroke." (PMID 32447613, 2021). "In conclusion we show that stroke increases the number of SOM+/NPY+ interneurons in the whole striatum during the recovery phase, likely in interneurons expressing SOM and/or NPY under undetectable levels in the uninjured brain." (PMID 32447613, 2021). "In plasma, NPY levels were significantly lower compared to the control group in the acute phase of female stroke patients." (PMID 28082897, 2016). "Second, this was a cross-sectional study and the serum levels and mRNA of NPY measured at the acute stage of stroke patients, hence, the long-term dynamic evolution process of these biological characters is not known." (PMID 28082897, 2016). "MDD patients had decreased NPY protein and mRNA caused by chronic stress, while PSD patients mixed acute stress of stroke which leads to a transitory rise of mRNA, but the protein had no time to be affected for simultaneously collected blood samples." (PMID 28082897, 2016). "Neuropeptide Y (NPY) has been reported to be involved in the pathophysiology of several cardiovascular disease processes and might contribute to the incidence of stroke, but the prognostic utility of circulating NPY after acute ischaemic stroke is unclear." (PMID 39575855, 2025). "In the present study, the significant association of plasma NPY with clinical outcomes was independent of well‐established risk factors for poor stroke prognosis, such as age, sex, admission NIHSS score, medical history and ischaemic stroke subtype." (PMID 39575855, 2025). "In recent years, the relationship between NPY and stroke has also been widely reported." (PMID 34422139, 2021). "Whether the increase of SOM+ and/or NPY+ interneurons represents one of the mechanisms behind spontaneous neurological recovery after stroke is an attractive hypothesis to be proved in future studies." (PMID 32447613, 2021). "Furthermore, this effect seems to be influenced by the stroke-damaged brain area in which SOM/NPY cell number is evaluated, resulting in a delay in the cortex (40 days for complete recovery) and complete absence in the hippocampus (no recovery after stroke)." (PMID 32447613, 2021). "Moreover, studies also demonstrated that NPY increased around brain lesions in animal models, and that administration of NPY following stroke increased infarct volume and reduced reperfusion, indicating that NPY is an important contributor in stroke biology." (PMID 39575855, 2025).
Stroke (continued). "Furthermore, NPY levels in patients with intracerebral and subarachnoid haemorrhage were reported to be positively correlated with the severity of disease, and showed potential for predicting the occurrence of subsequent stroke due to vasospasm." (PMID 39575855, 2025). "Interestingly, in models of brain ischemia, there is a selective sparing of SOM/NPY expressing interneurons in striatum as demonstrated in a gerbil and in a rat model of global forebrain ischemia at different time points after stroke (4 days and 2–28 days respectively)." (PMID 32447613, 2021). "Although speculative, the results of our study showing an increase of SOM+/NPY+ interneurons 6 weeks after stroke suggest that these cells could also be part of a “neuroplastic response” after stroke that is important for spontaneous stroke recovery and that could be hampered by T2D." (PMID 32447613, 2021). "We demonstrated that stroke induces an increase in the number of SOM+ and NPY+ interneurons in the ipsilateral whole striatum of normal mice 6 weeks after stroke and that this effect is completely abolished by T2D." (PMID 32447613, 2021). "Importantly, our results show that stroke increased SOM+ and NPY+ cell number 6 weeks after stroke in SD mice while T2D prevented this stroke-dependent effect." (PMID 32447613, 2021). "However, we reported for the first time, that with longer time after stroke (6 weeks), the number of SOM and/or NPY expressing cell is further increased, exceeding also the baseline number." (PMID 32447613, 2021). "Although speculative, this observation of possible T2D-induced alteration of neuroplasticity involving SOM+/NPY+ interneurons could also open up for the possibility of developing new, targeted therapies to counteract negative effects of T2D on SOM+/NPY+ interneurons and facilitate stroke recovery." (PMID 32447613, 2021). "In addition, to test whether this spatial co-localization pattern is also observed in areas of Wallerian degeneration after stroke, human ischemic brain lesions were double-labeled for NPY-Y1R and axonal markers (data not shown)." (PMID 28302146, 2017).
chronic heart failure (10 papers, 2009 to 2025). "Elevated circulating NPY levels are associated with adverse outcomes in chronic heart-failure patients." (PMID 37162194, 2023). "We have recently shown that CS NPY levels are associated with adverse clinical outcomes in patients with stable chronic heart failure who are undergoing implantation of cardiac resynchronization devices." (PMID 35766271, 2022). "In humans, NPY levels predict cardiovascular complications in end-stage renal disease, and NPY is implicated in congestive heart failure." (PMID 19119412, 2009). "This cohort study examines whether myocardial neuropeptide Y levels in coronary sinus blood samples are associated with outcomes in patients with stable chronic heart failure." (PMID 31876927, 2020). "High cardiac sympathetic drive and release of the sympathetic cotransmitter neuropeptide Y (NPY) are significant features of congestive heart failure (CHF), in which resting venous NPY levels are known to be associated with mortality." (PMID 39861963, 2025). "Our results highlight that saxagliptin and NPY may interfere with cardiac tissue remodeling and thus play a role in the pathophysiological mechanisms of end-stage chronic heart failure." (PMID 35884882, 2022). "Chronic heart failure (CHF) is associated with increased sympathetic drive and may increase expression of the cotransmitter neuropeptide Y (NPY) within sympathetic neurons." (PMID 31876927, 2020).
endothelial dysfunction (10 papers, 2017 to 2025). In vascular diseases, endothelial dysfunction is a systemic pathological state of the endothelium (the inner lining of blood vessels) and can be broadly defined as an imbalance between vasodilating and vasoconstricting substances produced by (or acting on) the endothelium. "The correlation between NPY and nicotine exposure-associated endothelial dysfunction and the underlying mechanisms are unknown." (PMID 33708805, 2021). "However, further studies will be required to determine the precise mechanisms underlying the endothelial dysfunction-mediated NPY induction." (PMID 31379881, 2019). "Smoking can affect the expression of NPY, which can aggravate endothelial dysfunction and blood flow disorder induced by nicotine." (PMID 33708805, 2021). "Nicotine can increase the expression of NPY, suggesting that NPY is involved in nicotine-induced endothelial dysfunction." (PMID 33708805, 2021). "NPY promotes the storage of fats such as triglycerides and cholesterol and increases the source of lipoproteins, leading to oxidative stress and endothelial dysfunction." (PMID 33708805, 2021). "Endothelial dysfunction can stimulate the secretion of NPY and promote leukocyte chemotaxis, thus expanding vascular inflammation." (PMID 33708805, 2021). "This review examines the role of NPY in nicotine-induced endothelial dysfunction, with a focus on the relationship between the nicotine/NPY system and the occurrence and development of arteriosclerotic cardiovascular disease." (PMID 33708805, 2021). "Thus, NPY can affect nicotine consumption, and is a promising target for treating nicotine-induced endothelial dysfunction." (PMID 33708805, 2021). "While HAR could regulate hormone by decreasing NPY level and increasing MT level, it further reduces pathological factors through alleviating inflammatory injury and endothelial dysfunction, which provided preventive effects for latter I/R injury." (PMID 28479928, 2017). "Therefore, elevated levels of NPY, especially in patients with endothelial dysfunction, could pre‐dispose the patients to develop microvascular vasospasm." (PMID 37460913, 2023). "NPY may play a role as an enhancer in nicotine-induced endothelial dysfunction." (PMID 33708805, 2021). "Also, the mediator NPY suppresses p38/NF-κB in the heart and kidney, with CKD-related endothelial dysfunction also involving TLR4/NF-κB." (PMID 41325840, 2025). "Additionally, serum levels of neuropeptide Y (NPY), parathormone (PTH), and fibroblast growing factor 23 (FGF 23) are commonly increased in CKD and seem to promote endothelial dysfunction in brain microcirculation." (PMID 32664677, 2020). "In our study, NPY, CA, AngII, ET-1, CRP, IL-6, and TNF-α increased while MT decreased after SD, which is characteristic of the beginning of myocardial injury due to hormone disorders, inflammation, and endothelial dysfunction." (PMID 28479928, 2017).
Glucose intolerance (10 papers, 2014 to 2023). Glucose intolerance (GI) can be defined as dysglycemia that comprises both prediabetes and diabetes. "Our findings are generally consistent with previous studies demonstrating that maternal obesity causes lifelong weight gain and glucose intolerance associated with disruption in AgRP/NPY and POMC axonal projections during adulthood." (PMID 32163401, 2020). "We know of only one other study that described clear sex differences, with increased susceptibility in female offspring: prenatal metformin treatment to genetically obese neuropeptide Y-overexpressing dams caused adiposity and glucose intolerance in female but not male offspring at 7 months of age." (PMID 36112170, 2022).
ischemia (10 papers, 2018 to 2025). A hypoperfusion of the BLOOD through an organ or tissue caused by a PATHOLOGIC CONSTRICTION or obstruction of its BLOOD VESSELS, or an absence of BLOOD CIRCULATION. "A previous study found that infusing NPY into coronary arteries in humans caused ischemia ECG alterations and chest discomfort." (PMID 36012430, 2022). "Activation of sympathetic system predisposes to ischemia-induced VF that can be based on several mechanisms mediated by catecholamine-related as well as neuropeptide Y-related signaling." (PMID 33396934, 2020). "Increased plasma NPY was proved to contribute to post‐exercise ischaemia in coronary artery disease patients after accepting the bicycle exercise test." (PMID 39575855, 2025). "It was also found that VEGF production is stimulated by neuropeptide Y (NPY), whose serum levels increase during exercise, hypoxia, cold exposure, tissue injury, ischemia, and hemorrhagic shock." (PMID 35203690, 2022). "FLX treatment and ischemia have been shown to induce the production of CR+ and NPY+ cells from L1-INP cells in the rodent cerebral cortex." (PMID 31383032, 2019). "NPY is the most abundant neuropeptide in the heart and brain and it is released during nerve activity as well as during ischemia, leading to vasoconstriction and smooth muscle cell proliferation." (PMID 30254326, 2018). "The vasoconstrictive and pro-angiogenic properties of NPY have been found to perform compensatory or detrimental myocardial remodeling in response to hemodynamic overload and ischemia." (PMID 30283345, 2018). "Overall, NPY therefore seems to play a dual-role in worsening ischemia in the short term but potentially promoting angiogenesis in the longer term." (PMID 30283345, 2018). "In humans and animals, elevated plasma NPY levels were observed in several stress conditions including exercise, hypoxia, cold exposure, tissue injury, ischemia, and hemorrhagic shock, and dysregulation of NPY has been implicated in the pathophysiology of metabolic disorders." (PMID 30283345, 2018).
Parkinson disease (10 papers, 2014 to 2024). A progressive degenerative disorder of the central nervous system characterized by loss of dopamine producing neurons in the substantia nigra and the presence of Lewy bodies in the substantia nigra and locus coeruleus. "In patients with Parkinson’s disease, both the number and silver grain density of NPY mRNA-expressing cells were increased in the NAc and ventral part of the caudate nucleus and putamen." (PMID 34298907, 2021). "Numbers and densities of NPY mRNA-expressing cells in the NAc, caudate nucleus, and putamen were analyzed in healthy individuals and patients with Parkinson’s disease by in situ hybridization histochemistry." (PMID 34298907, 2021). "On the other hand, reports on nigrostriatal regulation in human brain with Parkinson’s disease show that NPY mRNA expression rises as a consequence of a dampened dopaminergic tone." (PMID 25324788, 2014). "Based of the data of our study this finding may suggest the involvement of NPY fibers in Parkinson’s disease." (PMID 31740757, 2019). "Ample evidence suggests that an imbalance in dopaminergic tone impacts the expression levels of neuropeptides like somatostatin (SST) and neuropeptide Y (NPY), as seen in patients with Parkinson’s disease and HD as well as in rodent models." (PMID 39468205, 2024). "Therefore, exogenous NPY has been suggested as a therapeutic strategy to stimulate the proliferation of progenitor and production of newly generated neurons for several neurodegenerative diseases including Alzheimer's and Parkinson's diseases (for review, sees 21)." (PMID 30984535, 2019).